WFDC1 (WAP four-disulfide core domain 1)
Description:
Has growth inhibitory activity.
Synonyms: PS20
Tractability: Antibody: UniProt places it where antibodies can reach, with high confidence; UniProt predicts a signal peptide or a membrane-spanning region; its Gene Ontology location is reachable by antibodies, with medium confidence.
Gene: Protein-coding gene on chromosome 16 (84,294,615 to 84,329,853, forward strand). Ensembl gene ENSG00000103175.
Subcellular location: Secreted
Gene Ontology:
Molecular function: peptidase inhibitor activity
Biological process: negative regulation of cell growth; regulation of cell growth
Cellular component: extracellular region
Genetic constraint (gnomAD): Loss-of-function variants: 39 observed, 29.76 expected, observed/expected ratio (o/e) 1.31, 90% interval 1.01 to 1.71. The synonymous counts are far from expectation, so gnomAD's model fits this gene poorly and the ratio says little. Missense variants: 386 observed, 270.34 expected, observed/expected ratio (o/e) 1.43, 90% interval 1.31 to 1.55. Synonymous variants: 184 observed, 124.39 expected, observed/expected ratio (o/e) 1.48, 90% interval 1.31 to 1.67.
Homologues: Orthologues: chimpanzee WFDC1 (99% identical), dog WFDC1 (88% identical), guinea pig WFDC1 (80% identical), mouse Wfdc1 (80% identical), rat Wfdc1 (80% identical), pig WFDC1 (79% identical), macaque WFDC1 (78% identical), tropical clawed frog wfdc1 (59% identical), zebrafish wfdc1 (56% identical).